MT-ND5 (mitochondrially encoded NADH:ubiquinone oxidoreductase core subunit 5)
Diseases named in the same sentence as MT-ND5 in open-access papers (continued):
Sharing a sentence is not in itself a finding about the gene and the disease.
hypertrophic cardiomyopathy (1 paper, 2021). A condition in which the myocardium is hypertrophied without an obvious cause. "Another patient (P11) negative to m.3243A > G was carrying m.13135G > A in MT-ND5 gene that is reported as possible hypertrophic cardiomyopathy susceptible factor." (PMID 33484326, 2021).
mitochondrial cytopathy (1 paper, 2024). "Hence, the diagnosis of MT-ND5-associated mitochondrial cytopathy due to the pathogenic variant m.13091T>C causing MELAS-like syndrome with tubulointerstitial nephropathy and childhood-onset optic neuropathy was confirmed." (PMID 39262552, 2024).
multiple mitochondrial dysfunctions syndrome 4 (1 paper, 2025). Any fatal multiple mitochondrial dysfunctions syndrome in which the cause of the disease is a mutation in the ISCA2 gene. "The resulting syndromes varied, with the most common being multiple mitochondrial dysfunction syndrome 4 (ISCA2) in 13.8%, achalasia addisonian alacrima syndrome (AAAS) in 8.6%, and mitochondrial complex I, III, V, or IV syndromes (TMEM70, MT-ND5, and ATP5MD, among others) in 12.9%." (PMID 40868553, 2025).
multiple sclerosis (1 paper, 2024). A progressive autoimmune disorder affecting the central nervous system resulting in demyelination. "Mutations in MT-ND5 12633C > A and MT-ND4 11719G > A genes were found in patients with multiple sclerosis." (PMID 39802950, 2024).
obsessive-compulsive disorder (1 paper, 2015). A disorder characterized by the presence of persistent and recurrent irrational thoughts (obsessions), resulting in marked anxiety and repetitive excessive behaviors (compulsions) as a way to try to decrease that anxiety. "The expression of other 5 protein-coding mitochondrial-encoded genes, MT-ND1, MT-ND5, MT-CO3, MT-ATP6, MT-ATP8, was found associated with the maternal psychopathology diagnosis of maternal obsessive compulsive disorder, maternal weight and with infant birth measures." (PMID 26418562, 2015).
psoriasis (1 paper, 2025). An autoimmune condition characterized by red, well-delineated plaques with silvery scales that are usually on the extensor surfaces and scalp. "P. clypearia may ameliorate inflammation in psoriasis mice by modulating genes such as Hspa1a, Hspa1b, mt-Nd4l, mt-Nd5, mt-Nd6, Bcl2, Asns, Trib3, and associated pathways related to energy metabolism, cell growth, and apoptosis." (PMID 41385507, 2025). "The results indicated that P. clypearia may affect the energy metabolism, cell growth and apoptosis by regulating genes such as Hspa1a, Hspa1b, mt-Nd4l, mt-Nd5, mt-Nd6, Bcl-2, Asns, Trib3, GzmA, CTSG, etc, thereby mitigating psoriasis-related inflammation." (PMID 41385507, 2025). "Our study demonstrated that IMQ downregulated mt-ND4L, mt-ND5, and mt-ND6, while ESW administration could reverse this effect, indicating that ESW may improve psoriasis inflammation by regulating mitochondria and energy metabolism." (PMID 41385507, 2025).
rectal adenocarcinoma (1 paper, 2017). "On the other hand, the MT-ND5 gene has been reported to carry the majority of truncating mutations in colon or rectal adenocarcinoma, and was associated with mitochondrial respiratory chain deficiency." (PMID 29137431, 2017).
rectal cancer (1 paper, 2023). A primary or metastatic malignant neoplasm that affects the rectum. "Of the 13 protein-coding genes, MT-ND5 had the highest number of variants in plasma EVs from both colon and rectal cancer patients." (PMID 37438741, 2023). "Based on mutations per kilobase, MT-ND5 and MT-ND4 were also the most affected in WB and FFPE tissue samples, respectively, from the rectal cancer patients." (PMID 37438741, 2023).
Thiamine deficiency (1 paper, 2025). Thiamine deficiency is a condition that occurs due to not enough thiamine (vitamin B1). "This case highlights the diagnostic challenges posed by MT-ND5 mutations, which can mimic other metabolic disorders such as thiamine deficiency." (PMID 41523412, 2025). "These diagnostic challenges are exemplified in the present case, in which a young child exhibited overlapping radiographic and clinical features that initially suggested thiamine deficiency but were ultimately attributable to an MT-ND5 pathogenic variant." (PMID 41523412, 2025).
tumor (39 papers, 2007 to 2026). "OSCC cells exhibited strong upregulation of COX-2 and mitochondrial genes (MT-ND2, MT-ND4, MT-ND5, and cytochrome b), indicating increased metabolic activity, a hallmark of tumor progression." (PMID 40061903, 2025). "Taken together, these data demonstrate that in a heteroplasmy-dependent fashion, Mt-Nd5 mutation is sufficient to remodel the tumor microenvironment and promote an anti-tumor immune response." (PMID 38286828, 2024). "Next Generation sequencing data reveals a mt-ND1 SNP variant, 3695 AC>A and an mt-ND5 SNP variant, 12871 G>A, in a primary R12 tumor in the near equivalent of 17%." (PMID 32010429, 2020). "Similar to the preceding tumor transplants, the mt ND5 SNP variant, 12871 G>A remained conserved at the same frequency (17%)." (PMID 32010429, 2020). "Alternatively, the mt ND5 SNP variant, 12871 G>A, remained at a frequency of 17%, in all the tumor transplants." (PMID 32010429, 2020). "An interesting case has been described of a disruptive frameshift mtDNA mutation affecting MT-ND5 that was inherited at low heteroplasmy in the family of a patient where it became homoplasmic in a tumor of this individual." (PMID 22299657, 2012). "Heteroplasmic MT-ND5 mutations may confer an adaptive advantage by enabling metabolic plasticity, and this advantage is more pronounced in physiological tumor environments." (PMID 40671877, 2025). "Tumours derived from cybrids harbouring a heteroplasmic m.12417insA frameshift mutation in MT‐ND5 showed increased levels of mitochondrial ROS coupled with enhanced apoptotic resistance and increased tumour growth in comparison to their homoplasmic counterparts." (PMID 35842901, 2022). "In addition, only 1 heteroplasmic somatic variant, m.13676 A>G (MT-ND5), was observed in 1 tumor specimen." (PMID 29137431, 2017). "Among the somatic variants, only m.13676 A>G (MT-ND5), found in only 1 tumor, was heteroplasmic." (PMID 29137431, 2017). "However, five genes (MT-CO1, MT-CYB, MT-DLOOP1, MT-ND1 and MT-ND5) not only presented germline variants, but also different somatic variants exclusive to tumor and internal control groups, indicating a possible association of such genes and variants with tumor development." (PMID 31673122, 2019). "We next examined the impact of MT-ND5 heteroplasmy on tumor growth in vivo using a mouse xenograft model." (PMID 40671877, 2025). "When grafted into mice, Hcmel12 cytoLbNOX and catalytic mutant tumors demonstrated comparable time to endpoint and tumor weight at endpoint as wild-type or Mt-Nd5 mutant tumors." (PMID 38286828, 2024). "In this analysis, we observed a statistically significant difference between all groups, with tumor group presenting more heteroplasmic variants in MT-RNR1, MT-ND5, MT-ND4, MT-ND2, MT-DLOOP1 and MT-CO1." (PMID 31673122, 2019). "Further, the higher rate of heteroplasmic variants in tumor groups was statistically significant in six of such regions: MT-RNR1, MT-ND5, MT-ND4, MT-ND2, MT-DLOOP1 and MT-CO1." (PMID 31673122, 2019). "In addition to the shared variants, MT-ND5 also presents a high rate of exclusive variants not only in tumor samples but also in internal control samples, suggesting that this gene could also be altered in cells in other adjacent organs of cancer patients, contributing to possible tumor advances." (PMID 31673122, 2019). "Regarding the mitochondrial genes in which most of the tumor-exclusive variants were found, we observed that MT-DLOOP2, MT-DLOOP1 and MT-ND5 were among the regions with more variants in at least half of the tumor samples included in this analysis." (PMID 31673122, 2019). "Tumor also presented substantially more variants in the following regions: MT-RNR1, MT-ND5, MT-ND4, MT-ND2, MT-DLOOP1 and MT-CO1." (PMID 31673122, 2019).
tumor (continued). "A 3D line graph shows the appearance and conservation of two “de-novo” SNP variants, mt-ND1 3695 AC>A and mt-ND5 12871 G>A, which were not present in normal R12 or controls but later appeared in subsequent R12 tumor clone transplants." (PMID 32010429, 2020). "Notably, there was a trend toward enhanced tumor growth in the presence of MT-ND5 heteroplasmy." (PMID 40671877, 2025). "In addition, the genes with more variants were: (i) for tumor-exclusive variants, MT-DLOOP1 and MT-DLOOP2 (with 16% each); (ii) for variants exclusive to internal control, MT-ND5 (with 25%); and (iii) for variants shared by both groups, MT-DLOOP1 (with 22%) and MT-ND5 (with 19%)." (PMID 31673122, 2019). "Seven-mutated genes detected from bcWES data are detected in single cells of either primary tumor or lymph node (fdr2d<0.2): MT-RNR2, MT-RNR1, MT-ND5, MT-TI, HUWE1, TMEM219 and INTS8." (PMID 31028395, 2019). "The most interesting observation was that two unrelated tumor samples (MKG11 and MKG21) exhibited frame-shift causing length heteroplasmy in MT-ND5 on position 12390, which was not seen in the associated benign samples." (PMID 26262956, 2015).
cancer (24 papers, 2011 to 2026). A tumor composed of atypical neoplastic, often pleomorphic cells that invade other tissues. "This pathway, connecting mitochondrial dysfunction to epigenetic alterations, offers a plausible explanation for the increased pro-cancer effects observed following MT-ND5 mutations." (PMID 40671877, 2025). "Our results demonstrate that MT-ND5 mutations drive cancer progression by increasing cellular ROS and genome instability, and by altering the redox balance and epigenetic landscapes." (PMID 40671877, 2025). "An impactful study demonstrated the first application of DdCBE technology in cancer research by generating murine melanoma models with engineered truncating MT-ND5 mutations at heteroplasmy levels of 40%, 60% or 80%." (PMID 41303661, 2025). "This study revealed that the induced truncating mutations in MT-ND5 are advantageous in nascent cancer cells, at least in kidney cells." (PMID 40671877, 2025). "In this context, we showed that exposure to cisplatin of cancer cells of gynecological origin induced the occurrence of m.13828C>T/MT-ND5 and the m.8156G>T/MT-CO2 mutations." (PMID 29735924, 2018). "Forced overexpression of mutant forms of MT-ND5 or MT-ND2 with missense mutations in cancer cells carrying wild type mtDNA increases ROSproduction, confers a growth advantage and stimulates aerobic glycolysis through hypoxia-inducible factor 1α (HIF1α)." (PMID 29735924, 2018). "We speculate that the upregulation of NAMPT and increased glycolysis in established cancers may serve as compensatory mechanisms to restore NAD+ levels in response to Complex I deficiency caused by MT-ND5 mutations." (PMID 40671877, 2025). "Hotspot truncating mutations in mitochondrial complex I genes are a common feature of several cancers, with truncating mutations in complex I (MT-ND5 in particular) being over-represented compared with mutations in genes encoding respiratory complexes III, IV and V3." (PMID 38286828, 2024). "MT-ND5 is the most frequently mutated mitochondrial gene in cancer." (PMID 37438741, 2023). "However, it has been also reported that cancer cells harboring a nonsense mtDNA mutation in MT‐ND5 displayed a likely ROS‐mediated compensatory mitochondrial biogenesis orchestrated by PGC‐1α upregulation, which in turn favors cancer cell growth." (PMID 34606156, 2022). "In fact, mutations in MT-ND4 and MT-ND5 leading to complex I dysfunction have been previously associated with procancerous phenotypes and tumorigenesis in different types of cancer, although the particularities of this relationship are still unknown." (PMID 35183124, 2022). "The MT-ND5 gene, encoding NADH dehydrogenase 5—a subunit of Complex I—is the most commonly mutated mtDNA gene in HGSOC and across most other cancer types." (PMID 41303661, 2025). "The somatic variants identified in our cohort and those found in cancers of MITOMAP both showed enrichment on D-loop and MT-ND4, while our results were additionally enriched on MT-ND1 and MT-ND5." (PMID 38566210, 2024). "In this study, our analyses with multiple types of cancer have highlighted different mtDNA mutations, particularly in the MT-ND4, MT-ND5 and D-loop, suggesting a special importance of such mitochondrial mutations and regions during cancer development and progression." (PMID 35183124, 2022). "We also highlighted that most shared variants were in the MT-ND4, MT-ND5 and D-loop, and that some of these variants were nonsynonymous, indicating a special importance of these variants and regions regarding cancer progression, involving genomic and epigenomic alterations." (PMID 35183124, 2022). "Upon FASTKD4 depletion, the MT-ND5-CYB precursor accumulates, accompanied by a decrease insome mature transcript levels, including MT-ND5 and MT-CYB.The exact mechanism of TBRG4 in cancer is still under constant research." (PMID 36518140, 2022).
mitochondrial disease (18 papers, 2011 to 2025). "Early recognition, multidisciplinary care, and genetic counseling remain central to optimizing outcomes in MT-ND5-associated mitochondrial disease." (PMID 41523412, 2025). "MTND5 can catalyze the synthesis of NADH-ubiquinone oxidoreductase complex I at an early stage, and MTND5 deletion or mutation is associated with various mitochondrial diseases." (PMID 39625960, 2024). "We generated a mouse model with the m.G12918A mutation in the MT-ND5 gene, associated with mitochondrial genetic disorders in humans." (PMID 36224582, 2022). "As a model of mitochondrial diseases, we used transmitochondrial cybrids harboring wild-type mtDNA and two disease-causing mutations: m.13513 G > A (MT-ND5) and m.8344 A > G (MT-tRNA-Lys)." (PMID 40790102, 2025). "A recent case report stated that two cases of MT-ND5-related mitochondrial disease were misdiagnosed as seronegative neuromyelitis optical spectrum disorder." (PMID 39095827, 2024). "Although many of these genes have not been well-studied, the MT-ND5 gene, involved in encoding complex I, has been found to be especially susceptible to mutations and has been linked to multiple mitochondrial diseases with varying phenotypic presentations." (PMID 41523412, 2025). "Therefore, a mitochondrially encoded ND5 (MT-ND5) gene mutation causes mitochondrial oxidative phosphorylation (OXPHOS) disorder, resulting in the development of mitochondrial diseases." (PMID 36941957, 2023).
infection (8 papers, 2009 to 2025). The state of being infected such as from the introduction of a foreign agent such as serum, vaccine, antigenic substance or organism. "This infection upregulated certain gene expressions, such as ATP5PF, ATP6, COX1, MT-ND5, CYTB, and HIF-1α and downregulated CACNA1B and RYR3 expression." (PMID 41157602, 2025).
psychiatric disorder (2 papers, 2025). A disorder characterized by behavioral and/or psychological abnormalities, often accompanied by physical symptoms. "Moreover, mutations in MT-ND6 and MT-ND5, both components of NADH dehydrogenase, have been associated with various psychiatric disorders." (PMID 40495250, 2025).
Kidney (1 paper, 2022). "The amino acid change associations were previously predicted between Prost-AdenoCA and MT-ND5 (13789 T > C, Y485H), Kidney-RCC and MT-ND6 (14178 T > C, I166V), and Kidney-ChRCC and MT-ATP6 (8584 G > A, A20T)." (PMID 35183124, 2022).
MT-ND5 also shares sentences with these, for which no sentence is quoted: Leber hereditary optic neuropathy (9 papers); Parkinson disease (9); lactic acidosis (7); colorectal cancer (4); cyst (3); MERRF (3); schizophrenia (3); Stroke (3); thyroid cancer (3); Anxiety (2); bipolar disorder (2); colon cancer (2); dyslipidemia (2); glaucoma (2); Huntington disease (2); leukemia (2); metabolic disorders (2); mitochondrial encephalopathies (2); myoclonic epilepsy with (2); neurodegenerative disease (2); onchocerciasis (2); overlap syndromes (2); acute myeloid leukemia (1); Alpers syndrome (1); amyotrophic lateral sclerosis (1); asthma (1); Ataxia (1); autonomic dysfunction (1); bladder cancers (1); Brain atrophy (1).
A further 62 diseases each share a sentence with MT-ND5 in 1 paper.